CHRNA5 (cholinergic receptor nicotinic alpha 5 subunit)
Description:
Component of neuronal acetylcholine receptors (nAChRs) that function as pentameric, ligand-gated cation channels with high calcium permeability among other activities. nAChRs are excitatory neurotrasnmitter receptors formed by a collection of nAChR subunits known to mediate synaptic transmission in the nervous system and the neuromuscular junction. Each nAchR subunit confers differential attributes to channel properties, including activation, deactivation and desensitization kinetics, pH sensitivity, cation permeability, and binding to allosteric modulators. Has an accessory rather than functional role and is only able to form functional nAChRs when co-assembled with another beta subunit. Participates in pentameric assemblies along with CHRNA3, CHRNA4, CHRNB2 and CHRNB4. Increases receptor sensitivity to acetylcholine and nicotine when associated with CHRNA4 and CHRNB2. Plays a role in nicotine addiction.
Synonyms: LNCR2
Tractability: Small molecule: a drug acting on it is in phase 2 or 3 trials; a high-quality ligand is known; it belongs to a druggable protein family. Antibody: its Gene Ontology location is reachable by antibodies, with high confidence; UniProt places it where antibodies can reach, with medium confidence; UniProt predicts a signal peptide or a membrane-spanning region. PROTAC: ubiquitination databases record sites on it; a small molecule that binds it is known.
Safety:
Unwanted effects reported when the protein is acted on. In parentheses: how it was acted on, where the effect was seen, and who reports it.
addiction (source: ClinPGx)
cocaine dependence (source: ClinPGx)
nicotine dependence (source: ClinPGx)
response to smoking cessation therapies (source: ClinPGx)
smoking addiction (source: ClinPGx)
Gene: Protein-coding gene on chromosome 15 (78,565,520 to 78,595,269, forward strand). Ensembl gene ENSG00000169684.
Subcellular location: Synaptic cell membrane; Cell membrane
Subcellular location (Human Protein Atlas): Focal adhesion sites; Plasma membrane
Pathways (Reactome):
Neuronal System: Highly calcium permeable nicotinic acetylcholine receptors; Highly calcium permeable postsynaptic nicotinic acetylcholine receptors
Gene Ontology:
Molecular function: acetylcholine receptor activity; acetylcholine-gated monoatomic cation-selective channel activity; protein binding; ligand-gated monoatomic ion channel activity; neurotransmitter receptor activity; extracellular ligand-gated monoatomic ion channel activity; monoatomic ion channel activity; transmembrane signaling receptor activity
Biological process: acetylcholine receptor signaling pathway; behavioral response to nicotine; calcium ion transport; chemical synaptic transmission; membrane depolarization; monoatomic ion transmembrane transport; neuromuscular synaptic transmission; presynaptic modulation of chemical synaptic transmission; response to nicotine; signal transduction; synaptic transmission, cholinergic; chemical synaptic transmission, postsynaptic; excitatory postsynaptic potential; monoatomic ion transport; regulation of postsynaptic membrane potential
Cellular component: acetylcholine-gated channel complex; plasma membrane; neuron projection; presynaptic membrane; synapse; synaptic membrane; cholinergic synapse; dopaminergic synapse; membrane; postsynaptic membrane
Genetic constraint (gnomAD): Loss-of-function variants: 18 observed, 27.97 expected, observed/expected ratio (o/e) 0.64, 90% interval 0.44 to 0.95. The upper end of that interval is the gene's LOEUF score, 0.95, which puts it in group 4 of 6, group 1 being the genes least tolerant of losing a copy. Missense variants: 407 observed, 514.19 expected, observed/expected ratio (o/e) 0.79, 90% interval 0.73 to 0.86. Synonymous variants: 166 observed, 182.05 expected, observed/expected ratio (o/e) 0.91, 90% interval 0.8 to 1.04.
Homologues: Orthologues: chimpanzee CHRNA5 (99% identical), macaque CHRNA5 (99% identical), pig CHRNA5 (92% identical), dog CHRNA5 (89% identical), rat Chrna5 (89% identical), mouse Chrna5 (89% identical), rabbit CHRNA5 (88% identical), guinea pig CHRNA5 (83% identical), tropical clawed frog chrna5 (79% identical), zebrafish chrna5 (70% identical). Paralogues in human: CHRNB3 (63% identical), CHRNA2 (50% identical), CHRNA4 (50% identical), CHRNA3 (46% identical), CHRNA6 (45% identical), CHRNA1 (43% identical), CHRNB4 (40% identical), CHRNB2 (39% identical), CHRNB1 (35% identical), CHRNA7 (33% identical), CHRND (33% identical), CHRNA10 (32% identical), and 33 more.
Diseases named in the same sentence as CHRNA5 in open-access papers:
CHRNA5 is named in the same sentence as 73 diseases in open-access papers, as found by Europe PMC text mining. Sharing a sentence is not in itself a finding about the gene and the disease. The quoted sentences say what the papers report.
nicotine dependence (93 papers, 2008 to 2026). Physical and psychological dependence on nicotine. "Nicotine addiction has a genetic component; the rs503464 single nucleotide polymorphism (SNP) in the CHRNA5 gene is associated with smoking cessation therapy success." (PMID 41808243, 2026). "Genetic variants like CHRNA5 rs16969968 and stoichiometric differences among nAChR subtypes are identified as critical determinants of individual susceptibility to nicotine dependence." (PMID 41179996, 2025). "rs16969968 is the primary Single Nucleotide Polymorphism (SNP) in CHRNA5 strongly associated with nicotine dependence and schizophrenia in humans." (PMID 39824806, 2025). "rs16969968 is the primary SNP in CHRNA5 that is strongly associated with nicotine dependence and smoking-related behaviors." (PMID 39824806, 2025). "The loss-of-function mutation (D398N) at the CHRNA5 gene rs16969968 locus increases nicotine addiction risk by reducing receptor calcium permeability, while VTA dopamine neurons in α5-knockout mice exhibit attenuated responsiveness to nicotine." (PMID 41179996, 2025). "Multiple studies have linked a genetic variant in CHRNA5 exon 5 (rs16969968) with susceptibility to lung cancer, both through indirect effects on nicotine dependence and smoking behaviour, and through direct tumour cell-intrinsic effects." (PMID 40336011, 2025). "Another SNP within CHRNA5 (rs588765) was also implicated in nicotine dependence by manipulating the expression of CHRNA5." (PMID 38862938, 2024). "The most significant association with nicotine dependence has been reported for the rs16969968 polymorphism in the CHRNA5 gene." (PMID 38862938, 2024). "Genome variants such as rs16969968 in CHRNA5 have been strongly associated with increased nicotine dependence and with a higher risk of developing a nicotine addiction." (PMID 37628681, 2023). "The associations have been found between the rs1051730 A allele of CHRNA3/the rs16969968 A allele of CHRNA5 and nicotine dependence." (PMID 37906564, 2023). "Several genes are associated with nicotine addiction, such as CHRNA5, which codifies a subunit of the nicotine receptor of acetylcholine (nAchR)." (PMID 37372959, 2023). "Chrna3 is part of a locus on chromosome 15q25 with Chrna5 and Chrnb4, which has also been identified in human GWASs to be associated with smoking-related behaviors and nicotine dependence." (PMID 37295945, 2023). "Among the many identified genetic variants of nicotine dependence, the variants in the CHRNA5/A3/B4 gene cluster on chromosome 15 that encode the α5, α3, and β4 subunits have recently received a lot of attention." (PMID 36078193, 2022). "Some clinical studies have identified polymorphic A allele of CHRNA5 rs16969968 as a risk factor for high nicotine dependence in Caucasians." (PMID 35222535, 2022). "The reproducibility of the research showing the genetic link between the variants in the CHRNA5/A3/B4 gene cluster and nicotine addiction further increases the power of these findings." (PMID 36078193, 2022). "This is why variants in the CHRNA5/A3/B4 cluster play a role in nicotine addiction through the aversive effect of nicotine on the mHb-IPN pathway when there are few reports of nicotine enhancement in the ventral tegmental (VTA) DA neurons." (PMID 36078193, 2022). "For example, carriers of the risk allele for nicotine addiction (rs17486278) have lower methylation of cg19696491/cg22563815 at CHRNA5, which increases smoking exposure and the resultant risk of lung cancer." (PMID 33752734, 2021). "The CHRNA5 single-nucleotide polymorphism (SNP) rs16969968 is strongly associated with nicotine dependence and lung diseases." (PMID 34206324, 2021). "Several well-known nicotine-addiction-associated genes, including CHRNA5, PSMA4, and CHRNA3, were identified and their cross-brain-tissue-association patterns were revealed." (PMID 35052378, 2021).
nicotine dependence (continued). "Our study suggests that CHRNA5 rs16969968 polymorphism is associated with a significant increase of lung adenocarcinoma risk and with a nicotinic addiction." (PMID 32257438, 2020). "One of the most promising findings is that variants in the CHRNA5/A3/B4 cluster on chromosome 15q24 are associated not only with nicotine dependence (ND) but also with SCZ." (PMID 32012119, 2020). "Cholinergic Receptor Nicotinic Alpha 5 (CHRNA5) is an important susceptibility locus for nicotine addiction and lung cancer." (PMID 30543688, 2018). "The CHRNA5/A3/B4 gene locus is associated with nicotine dependence and other smoking related disorders." (PMID 30453884, 2018). "Numerous GWAS have identified the CHRNA5/CHRNA3/CHRNB4 gene cluster as the region harboring the strongest association with nicotine dependence." (PMID 30453884, 2018). "Composition of nicotinic receptors and tissue selective genetic effects of CHRNA5/A3/B4 regulatory variants impinged on nicotine addiction in the reward circuit." (PMID 30453884, 2018). "In this study, we tested the involvement of nAChR subunit polymorphisms in nicotine dependence and the response to smoking-cessation therapy, and found an association of CHRNA5 SNPs with both phenotypes." (PMID 29196725, 2017). "Another study found that rs11636753 G allele was significantly associated with decreased CHRNA5 DNA methylation, lower CHRNA5 expression and increased the risk of nicotine dependence." (PMID 27926527, 2017). "An association between the nonsynonymous variant rs16969968 in CHRNA5 and nicotine dependence was first reported in 2007 in a candidate gene study, with the minor allele found to confer increased risk." (PMID 26866486, 2016). "An association between the SNP rs16969968 in CHRNA5 and nicotine dependence was first reported in 2007 in a candidate gene study." (PMID 27871728, 2016). "Genetic polymorphisms in the CHRNA5 is associated with intensity of smoking and nicotine dependence." (PMID 27344179, 2016). "The strongest association between nicotinic receptors and nicotine addiction is a non-synonymous change (rs16969968, D398N) in the gene encoding the α5 subunit of the nicotinic receptor (CHRNA5) on chromosome 15." (PMID 26270548, 2015). "For instance, the minor allele of rs16969968, a missense variant in CHRNA5, increases risk for the development of nicotine dependence, and independently decreases risk for cocaine dependence." (PMID 26270548, 2015). "In contrast, for the missense CHRNA5 SNP rs16969968 that has reproducible associations with both nicotine dependence and CPD,5, 6, 7 the lowest P-value, by far, was observed for CPD (P=9.4 × 10−24)." (PMID 26440539, 2015). "CHRNA5, located at the 15q25.1 lung cancer susceptibility locus, is an attractive candidate gene for smoking behavior, nicotine dependence, and smoking-related disease, as they have been plausibly linked with carcinogenesis." (PMID 25329654, 2014). "The CHRNA5 risk polymorphism (rs16969968) also has a significant association with nicotine addiction strength (level of physical addiction) with different allelic expression conferring either increased or decreased levels of nicotine dependence." (PMID 25642160, 2014). "Previous studies have demonstrated that del allele homozygotes at rs3841324 have a 2.9-fold increase in CHRNA5 mRNA levels in the frontal cortex and that low levels of CHRNA5 mRNA are associated with a lower risk for nicotine dependence and lung cancer." (PMID 25329654, 2014). "We investigated six variants known to influence nicotine addiction or alcohol metabolism, including rs16969968 (CHRNA5), rs578776 (CHRNA3), rs1229984 (ADH1B), rs698 (ADH1C), rs1573496 (ADH7), and rs4767364 (ALDH2)." (PMID 24505444, 2014). "In Indian subjects, variations in the CHRNA5 risk polymorphism (rs16969968) are associated with increased probability of nicotine dependence." (PMID 25642160, 2014).
nicotine dependence (continued). "Results show that nicotine dependence is a mediator of the association between lung adenocarcinoma and gene variations in the regions of CHRNA5/A3/B4 and accounts for approximately 15% of this relationship." (PMID 25233467, 2014). "Our findings suggest that nicotine dependence plays an important role between genetic variants in the CHRNA5/A3/B4 region, especially CHRNA3, and lung adenocarcinoma." (PMID 25233467, 2014). "In our study, the majority of SNPs in the CHRNA5/A3/B4 region are significantly associated with both nicotine dependence and lung ADC risk." (PMID 25233467, 2014). "The CHRNA5/A3/B4 gene cluster encoding the α5, α3 and β4 subunits of the nAChRs is the major genomic locus associated with nicotine dependence in humans." (PMID 25384568, 2014). "When the major allele occurs on the low mRNA expression haplotype of CHRNA5, the risk for nicotine dependence and lung cancer is significantly lower when compared to major alleles on the higher mRNA expression haplotype." (PMID 24303001, 2013). "Recent human genetic association studies identified variants in the CHRNA5 gene encoding the α5 nAChR subunit have the risk of developing ethanol or nicotine dependence." (PMID 23869214, 2013). "We recently showed that CA and the interaction of CA with a functional variant rs16969968 at CHRNA5 increased the risk for nicotine dependence in EAs." (PMID 23799031, 2013). "Gene association studies in humans have linked the α5 subunit gene CHRNA5 to an increased risk for nicotine dependence." (PMID 22380605, 2012). "A study using haplotype analysis with variants in the CHRNA5-CHRNA3-CHRNB4 gene cluster reported that variation in this cluster is associated with severity of nicotine dependence among long-term smokers who began daily smoking at age 16 or younger." (PMID 22438940, 2012). "Variants flanking and within the CHRNA5-CHRNA3-CHRNB4 gene cluster region affect the risk for nicotine dependence, and are also involved in the transition toward heavy smoking in mid-adulthood and in smoking persistence." (PMID 22438940, 2012). "Multiple genome-wide and targeted association studies reveal a significant association of variants in the CHRNA5-CHRNA3-CHRNB4 (CHRNA5/A3/B4) gene cluster on chromosome 15 with nicotine dependence." (PMID 20808433, 2010). "Recently, genetic association findings for nicotine dependence, smoking behavior, and smoking-related diseases converged to implicate the chromosome 15q25.1 region, which includes the CHRNA5-CHRNA3-CHRNB4 cholinergic nicotinic receptor subunit genes." (PMID 20700436, 2010). "The CHRNA5 subunit has been implicated as a potential risk factor for nicotine dependence resulting from an amino acid variant in a highly conserved region of the intracellular domain." (PMID 18783506, 2008). "This receptor is implicated in many of the long-term changes resulting from nicotine exposure during prenatal or early postnatal development, and the CHRNA5 gene coding for the α5 nAChR subunit is linked to nicotine addiction, schizophrenia, and effects of developmental nicotine exposure." (PMID 41249053, 2025). "Several genes are associated with nicotine addiction, such as CHRNA5 and ADAM33." (PMID 37372959, 2023). "Moreover, the SNP rs588765 was reported to be linked to changes in CHRNA5 mRNA expression in lung tissue and to show a strong relationship with nicotine dependence." (PMID 36276121, 2022). "Furthermore, recent studies have suggested bidirectional associations by revealing single nucleotide polymorphisms associated with nicotine dependence (CHRNA5) that are also associated with schizophrenia." (PMID 30515111, 2018). "And the level of CHRNA5 mRNA was associated with risk of nicotine dependence." (PMID 26831765, 2016).